KIT (KIT proto-oncogene, receptor tyrosine kinase)
Diseases named in the same sentence as KIT in open-access papers (continued):
Sharing a sentence is not in itself a finding about the gene and the disease.
cyst (4 papers, 2016 to 2025). A sac-like closed membranous structure that may be empty or contain fluid or amorphous material. "Exoc1 is essential for regulating cytoplasmic division in mice spermatocytes, and c-KIT facilitates cyst breakdown." (PMID 39833146, 2025). "Besides Notch signals, another important signaling pathway, KIT signaling pathway, has been demonstrated to promote germ cell cyst breakdown and determine oocyte numbers." (PMID 34174788, 2021).
ependymoma (4 papers, 2010 to 2025). A WHO grade II, slow growing tumor of children and young adults, usually located intraventricularly. "Endothelial cell KIT expression was associated with a young age at diagnosis of pilocytic astrocytoma or ependymoma, and it was occasionally present in histologically normal tissue of the fetus and children." (PMID 20030644, 2010). "When KIT mRNA expression was studied from seven ependymomas using mRNA in situ hybridization (4 of the 11 cases were uninformative), KIT mRNA was present in 6 (86%) cases in the tumor vessels." (PMID 20030644, 2010). "Marked (++ or +++) expression of KIT and phospho‐KIT were frequently present in the endothelia of ependymomas [6 (55%) out of 11, and 5 (45%) out of 11, respectively]." (PMID 20030644, 2010). "Four out of the five ependymomas with perinecrotic HIF‐1α expression showed moderate (++) expression of KIT in tumor endothelial cells." (PMID 20030644, 2010). "In anaplastic ependymomas endothelial cells and most of the abluminal cells of microvascular proliferations stained positively for phosphorylated KIT with uniform intensity." (PMID 20030644, 2010). "Four of the six ependymomas with KIT mRNA detected by in situ hybridization expressed endothelial cell KIT either moderately (++) or strongly (+++) in immunohistochemistry." (PMID 20030644, 2010). "Since tumor endothelial cell KIT and phosphorylated KIT tended to be more common in young children with pilocytic astrocytoma or ependymoma, we examined whether endothelial cell KIT expression might be present in the normal blood vessel endothelia during the fetal life and in young children." (PMID 20030644, 2010). "Nonetheless, the role of protein kinase signaling has been implied in ependymoma tumorigenesis, prompting several ongoing studies evaluating TKIs targeting RET, ALK, ROS, IGFR, PDGFR, FGFR, or EGFR, as well as inhibitors targeting PI3K, mTOR, KIT, and CDK4." (PMID 40238025, 2025).
erythroleukemia (4 papers, 2021 to 2022). Acute erythroid leukemia characterised by the presence of at least 50% erythroid precursors and at least 20% myeloblasts in the bone marrow. "It should therefore be investigated whether KIT mutations also contribute to human erythroleukemia." (PMID 34395414, 2021). "In addition, miR-221 has been found to lead to the minimization of stem cell repopulating activity in cord blood CD34+ cells by targeting KIT, while they also act as inhibitors in the proliferation process of erythroleukemia cell lines." (PMID 35163198, 2022). "To investigate whether the mechanism of KIT regulation is conserved in humans, we analyzed KIT expression in the BORIS-positive human erythroleukemia cancer cell line, K562." (PMID 34158481, 2021).
esophageal squamous cell carcinoma (4 papers, 2018 to 2023). Esophageal squamous cell carcinoma (ESCC) is a type of esophageal carcinoma (EC) that can affect any part of the esophagus, but is usually located in the upper or middle third. "In a single study, the expression of c-KIT in esophageal SCC was correlated with a worse prognosis, only being expressed in 29.9% of the specimens." (PMID 36851392, 2023).
Granuloma (4 papers, 2024 to 2025). A compact, organized collection of mature mononuclear phagocytes, which may be but is not necessarily accompanied by accessory features such as necrosis. "A diverse array of innate immune cells, including mast cells (MC) (cluster 20: HDC, CPA3, KIT), dendritic cells (DC) (cluster 23: CLNK, WDFY4, FLT3), neutrophils (FCGR3B, FFAR2, CSF3R), and macrophages (CD68, CD163, C1QA/B/C), was also present in these granulomas." (PMID 40772762, 2025). "Histopathology confirmed the exophytic mass to be a low-grade spindle-cell type gastrointestinal stromal tumour (GIST) with positive staining for KIT proto-oncogene markers CD117 and DOG1, whilst liver biopsies showed non-necrotising epithelioid granulomas consistent with sarcoidosis." (PMID 39030472, 2024).
Hepatic steatosis (4 papers, 2020 to 2024). Steatosis is a term used to denote lipid accumulation within hepatocytes. "Among downregulated genes (KIT, NTRK2, MAMDC2, and ANXA13), KIT could regulate apoptosis, NTRK2 was revealed that capable of activating apoptosis pathways with Brain derived neurotrophic factor (BDNF), which may promote the progression of fatty liver disease." (PMID 38665091, 2024).
lung squamous cell carcinoma (4 papers, 2015 to 2023). "Importantly, the data also demonstrated the potential activation of STAT3 by a number of upstream receptor tyrosine kinase signaling pathways found to be recurrently amplified in squamous cell lung carcinoma, including PDGFRA and/or KIT, EGFR, and FGFR1." (PMID 25573684, 2015).
lupus (4 papers, 2012 to 2023). "Three of these four drugs inhibit mast cell growth factor receptor tyrosine kinase KIT, suggesting that impaired KIT signaling might play a role in both drug-induced as well as systemic lupus erythematosus." (PMID 25276232, 2014).
medulloblastoma (4 papers, 2019 to 2022). A malignant, invasive embryonal neoplasm arising from the cerebellum. "The importance of KIT signaling for the regulation of HMOX1 expression can also be demonstrated in vitro in 661 W cells, which are derived from a medulloblastoma and whose gene expression profiles suggests a photoreceptor origin." (PMID 32242818, 2020).
metastasis (4 papers, 2016 to 2021). The spread or migration of cancer cells from one part of the body (where they first appeared) to another. "Thereby, synchronous lung metastasis more frequently showed mutations in ATM, KIT, PIK3CA and SMAD4 (each with 3/5 cases as compared to 1/5 cases with metachronous liver metastases)." (PMID 27756406, 2016). "Most SDH deficient GISTs have characteristic dumb bell/lobulated shape with thick fibrous bands, epithelioid morphology and frequent lymph node metastasis; SDH testing may precede KIT exon 11 mutation testing for suspected cases." (PMID 31538651, 2020).
mucinous colorectal adenocarcinoma (4 papers, 2015 to 2023). "In clinical CRC samples from mice, SCF/c-KIT signaling has been shown to promote mucus secretion in colonic goblet cells as well as the development of mucinous colorectal adenocarcinoma." (PMID 34440178, 2021). "Our previous study indicated that SCF/c‐KIT signaling promoted intestinal mucus secretion and development of mucinous colorectal adenocarcinoma by activating PKCδ‐MARCKS, therefore, future studies of this mechanism underlying the reduction in mucus thickness during aging are necessary." (PMID 33040455, 2020). "It was found that SCF/c-KIT signaling promotes the production of MUC2 and Mucinous Colorectal Adenocarcinoma (MCA) tumorigenesis by maintaining the expression of ATOH1." (PMID 38054820, 2023).
renal tumors (4 papers, 2015 to 2024). "However, despite IHC detection for c-kit in most ChRCCs and renal oncocytomas, no activating KIT mutations have been demonstrated in renal tumors." (PMID 32150988, 2020).
rheumatoid arthritis (4 papers, 2011 to 2024). A chronic, systemic autoimmune disorder characterized by inflammation in the synovial membranes and articular surfaces. "In this context, KIT (v-kit Hardy-Zuckerman 4 feline sarcoma viral oncogene homolog) and FMS (McDonough feline sarcoma viral (v-fms) oncogene homolog) kinases offer multiple potential therapeutic opportunities to control inflammation (rheumatoid arthritis) as well as cancer progression." (PMID 25460315, 2014).
small intestinal tumors (4 papers, 2013 to 2025). "Using a 1.60 cut-off point, KIT exon 9 mutated small intestine tumors could be differentiated with an AUC, sensitivity and specificity of 0.76 and 86.7% and 98.5%, respectively." (PMID 36359564, 2022). "The clinical, pathologic and genetic features of NF1-GISTs differ from those of sporadic GISTs, including the development of multiple small intestinal tumors, an absence of KIT and PDGFRA mutations, and an indolent nature." (PMID 26511941, 2016). "Incorporating molecular correlates such as KIT, PDGFRA, and MMR status in future cohorts will not only clarify the genetic landscape of small intestinal tumors but also strengthen the translational link between immunohistochemical features and targeted therapeutic strategies." (PMID 41465833, 2025).
T-cell lymphoma (4 papers, 2013 to 2022). "While KIT-immunolabeling (CD117) may be helpful in identifying an undifferentiated MCT, expression of KIT is not limited to MCs and is commonly observed in other round cell neoplasms, e.g., T-cell lymphomas." (PMID 34957277, 2021).
thyroid (4 papers, 2012 to 2026). "This miRNA, together with miR-221, targets p27kip1, p57, PTEN, TIMP3, and c-KIT, and it may play an essential role in thyroid carcinogenesis." (PMID 31636734, 2019). "Furthermore, these findings strengthen the importance of c-KIT expression as a marker of thyroid malignancy." (PMID 28301608, 2017). "The c-KIT expression-based classification is highly accurate and may provide a tool to overcome the difficulties in today's preoperative diagnosis of thyroid suspicious malignancies." (PMID 22233760, 2012). "In summary, we have demonstrated that c-KIT expression-based classification of thyroid lesions is highly accurate and may provide a tool to overcome the difficulties in today's preoperative diagnosis of thyroid suspicious malignancies." (PMID 22233760, 2012). "We investigated and correlated c-KIT expression levels and two known markers of thyrocytes differentiation, PAX8 and TTF-1, in malignant and benign cytological thyroid samples." (PMID 28301608, 2017).
urticaria (4 papers, 2018 to 2025). A vascular reaction of the skin characterized by erythema and wheal formation due to localized increase of vascular permeability. "We found significant trans-pQTL associations of the GCSAML urticaria-associated variant with plasma levels of five proteins encoded by TPSAB1, TPSB2, KIT, SELP, and SIGLEC6 (P-values < 1.0 × 10−7)." (PMID 37430141, 2023).
vascular tumors (4 papers, 2016 to 2022). "Miettinen M and colleagues have investigated c-KIT expression in malignant and benign vascular tumors in addition to fetal tissues." (PMID 34439864, 2021).
alopecia (3 papers, 2023 to 2025). Hair loss usually from the scalp. "The mechanism behind ripretinib-related alopecia remains unclear but may involve the inhibition of kinases such as KIT, PDGFRA, VEGFR2, and BRAF, all of which have been linked to hair loss." (PMID 40231257, 2025).
Autoimmunity (3 papers, 2014 to 2026). The occurrence of an immune reaction against the organism's own cells or tissues. "Star 27 should enable a reduction in FLT3-associated inflammation and autoimmunity while allowing KIT and CSF1R to compensate with classical DC maintenance." (PMID 25531068, 2014).
brain cancer (3 papers, 2021 to 2025). A primary or metastatic malignant neoplasm affecting the brain. "Within brain cancer cell lines in this cohort, high SNX10 expression was associated with resistance to a number of multitargeted RTK inhibitors, including pazopanib, tivozanib, and lenvatinib, which each target VEGFRs, PDGFRs, FGFRs, and KIT with varying selectivity." (PMID 36795488, 2023). "Since 2009, the FDA has approved a number of multi-kinase inhibitors that target angiogenic growth factor receptors (e.g., VEGFR, PDGFR, FGFR, RET, c-KIT, MET, AXL and others) for treatment of malignant diseases, including brain cancer." (PMID 40076810, 2025).
carcinoids (3 papers, 2012 to 2025). "All of the mutations in KIT were located in exon 11, which encodes the juxtamembrane domain, and were detected in two SQCC (variants p.E561K and p.T574del), one adenocarcinoma (p.Q575del), and one carcinoid (p.R586K)." (PMID 35884448, 2022).
Carney-Stratakis syndrome (3 papers, 2015 to 2020). Carney-Stratakis syndrome is a recently described familial syndrome characterized by gastrointestinal stromal tumors (GIST) and paragangliomas, often at multiple sites. "However, nearly 10–15% of adult GIST and 85% of pediatric GIST are negative for KIT and PDGFRA mutations, as called wild-type (WT) GIST, which is a component of the Carney-Stratakis syndrome caused by the succinyl dehydrogenase (SDH)-mutations." (PMID 33238982, 2020).
CNS germinoma (3 papers, 2022 to 2025). "In the present case, for the first time, we report a Chinese CNS germinoma patient with a KIT hotspot somatic mutation concurrent with a novel SDHA germline mutation that showed distinct early-onset." (PMID 35651799, 2022). "With the success of targeted therapy in other pediatric indications, KIT inhibition has recently emerged as an intriguing potential treatment approach for CNS germinoma." (PMID 39959669, 2025).
cryptorchidism (3 papers, 2018 to 2024). The failure of one or both testes of a male fetus to descend from the abdomen into the scrotum during the late part of pregnancy. "This is followed by the overexpression of KIT and the identification of three different variants for the diagnosis of SE (D816V (A/T); D816H (G/C); N822K (A/T)), which are also related to cryptorchidism." (PMID 37175579, 2023).
dysplastic nevi (3 papers, 2017 to 2022). "KIT expression was found in 6/7 Spitz, in all the mild-dysplastic nevi, and in 50% of the cases of junctional or compound nevi, whereas no positivity was encountered in dermal nevi." (PMID 34769348, 2021). "The literature data reveal ubiquitarian positivity of KIT in dysplastic nevi, as our findings suggest." (PMID 34769348, 2021).
esophageal melanoma (3 papers, 2015 to 2025). A melanoma affecting the esophageal wall. "Because the data are controversial due to the fact that BRAF/KRAS/KIT coexisting mutations were previously reported, particularly in primary esophageal melanomas, we attempted to explore the possible interaction of these three genes." (PMID 34769348, 2021). "Masitinib, which shares activity against KIT, PDGFR, and LYN, induced rapid regression, including central nervous system metastases, within four weeks in a KIT exon 11 mutant esophageal melanoma." (PMID 41301010, 2025).
follicular thyroid cancer (3 papers, 2016 to 2019). "We attribute our results to the fact that KIT signaling can promote cell proliferation and survival, while getting decreased in human follicular thyroid cancer." (PMID 31032340, 2019). "In addition, four KIT-mutant samples contained somatic single nucleotide variants in FRG1 (q < 0.01), a cancer driver gene in follicular thyroid cancer." (PMID 30867899, 2019).
Gynecomastia (3 papers, 2023 to 2024). Abnormal development of large mammary glands in males resulting in breast enlargement. "The proposed mechanism of gynecomastia, which is caused by dasatinib and imatinib, involves inhibiting the PDGFR and/or c-KIT." (PMID 39840195, 2024).
lentigo maligna melanoma (3 papers, 2021 to 2025). A skin cancer that usually develops in older, fair-skinned adults. "No KIT mutations were detected in lentigo maligna melanoma (LMM)." (PMID 33648909, 2021).
lung disease (3 papers, 2012 to 2021). "In KIT negative tumors, CD117 was expressed on scattered cytokeratin negative mast cells, which are prominent in remodeling lung disease." (PMID 23285214, 2012).
lymphopenia (3 papers, 2019 to 2021). Reduction in the number of lymphocytes. "Gender, performance status, the diameter of the primitive tumor, lymphopenia, polymorphonuclear (PMN) leucocytosis and KIT exon 11 PV type were found to be statistically significantly associated with PFS in univariable analyses." (PMID 33673554, 2021).
male infertility (3 papers, 2016 to 2021). The inability of the male to effect fertilization of an ovum after a specified period of unprotected intercourse. "As cell proliferation is crucial for the production of male germ cells and fertility, decreased expression of SCF or c-KIT in the testis and aberrant SCF/c-KIT signaling are associated with male infertility." (PMID 27738659, 2016). "The expression of miR-4485 was significantly downregulated in the asthenozoospermia patients compared to controls, and KIT, which acted as its target gene, was related to male infertility by bioinformatic analysis." (PMID 33746583, 2021). "Amongsperm factors, tr-KIT need to receive more attention inthe field of male infertility." (PMID 31210438, 2019).
malignant germ cell tumor (3 papers, 2014 to 2020). A gonadal or extragonadal malignant neoplasm that arises from germ cells. "Malignant germ cell tumors have a low mutational burden, but the KIT, KRAS, TGF-BMP, and Wnt-catenin signaling pathway inhibitors and anti-CD30 immunotherapy can be used as targeted therapies in patients with resistant disease." (PMID 33352733, 2020). "Certain immunohistochemical markers (OCT 3/4, c-KIT, TSPY, VASA) have been identified that can be useful in establishing the diagnosis of malignant germ cell tumors." (PMID 24731683, 2014).
melasma (3 papers, 2020 to 2025). "Compared to the control group, the melasma group showed extensive distribution of green fluorescence‐labeled c‐KIT and the red fluorescence‐labeled SCFs in the dermis." (PMID 40916844, 2025). "Overexpression of SCF and its receptor c‐KIT plays a crucial role in the facial pigmentation of melasma." (PMID 40916844, 2025). "Finally, we propose the targeting of SCF/KIT-inducible MITF-M expression as a strategy in the therapeutics for acquired pigmentary disorders such as melasma, freckles and senile lentigo." (PMID 31903124, 2020). "Western blotting consistently showed upregulation of c‐KIT and SCF in dermal cells in the melasma group compared to the control group." (PMID 40916844, 2025).
microphthalmia (3 papers, 2011 to 2020). Congenital or developmental anomaly in which the eyeballs are abnormally small. "Microphthalmia‐associated transcription factor has been reported to regulate KIT expression and is critical for mast cells differentiation." (PMID 29885053, 2018).
oligodendroglioma (3 papers, 2013 to 2023). A well-differentiated (WHO grade II), diffusely infiltrating neuroglial tumor, typically located in the cerebral hemispheres. "KIT receptor overexpressing tumours showed a rather different spectrum of morphological correlates, with expression significantly enriched in oligodendroglial tumours (14/37, 37.8% KIT positive cases oligodendroglial vs 50/235 negative, 21.3%, p = 0.0136, Fishers exact test)." (PMID 23990986, 2013).
rectal melanoma (3 papers, 2018 to 2025). "Patients with metastatic rectal melanoma harboring an activating c-KIT mutation may benefit from a targeted approach based on the use of tyrosine kinase inhibitors (TKIs)." (PMID 40978962, 2025). "Kit Mutation was reported in 35.5% of ano-rectal melanomas Not all tumors with KIT gene alterations are immunopositive for CD117 and its mutation frequency is high in ARMM." (PMID 29492238, 2018).
retinal degeneration (3 papers, 2019 to 2022). Degeneration of the retina. "Furthermore, the KIT signal was drastically reduced in mice homozygous for a retinal degeneration allele (rd10/rd10) which almost totally lack photoreceptor cells but not Müller glia cells." (PMID 32242818, 2020). "Here, we show in mouse models that signaling through the tyrosine kinase receptor KIT protects photoreceptor cells against both light-induced and inherited retinal degeneration." (PMID 32242818, 2020). "In summary, our findings provide strong evidence for KIT signaling in protecting photoreceptor cells against light-induced retinal damage as well as against inherited forms of retinal degeneration." (PMID 32242818, 2020).